MDM2 (MDM2 proto-oncogene)
Diseases named in the same sentence as MDM2 in open-access papers (continued):
Sharing a sentence is not in itself a finding about the gene and the disease.
tumor (continued). "Overall, these data strongly suggested that a single copy of chromosome 12 had acquired a fundamentally destabilized region around MDM2 in at least three, and possibly four, tumours." (PMID 24777035, 2014). "MDM2 was considered to be a valuable target for cancer therapy and MDM2 blockade with suitable antagonists was shown to block tumor growth in a number of models." (PMID 24955377, 2014). "Both Western blotting analysis on cell lysates and Immunohistochemical staining on the subcutaneous tumor tissues revealed that MDM2 were up-regulated with ATF3 forced expression." (PMID 25149542, 2014). "Several human tumor types have been shown to have increased levels of MDM2, including soft tissue sarcomas, bladder cancers, and osteosarcomas as well as breast tumors." (PMID 24955377, 2014). "Second, while the median levels of MDM2 and CDK4 expression were higher in ALT/WDL, the overlapping range of values for each tumor type is a limitation to the diagnostic usefulness of this test." (PMID 24965044, 2014). "It is known that the 309G variant is enhancing the binding of Sp1 transcription factor to its promoter, increasing therefore MDM2 expression and accelerating tumor formation." (PMID 24708820, 2014).
tumor (continued). "MDM2 was located in a region of high-level copy number (CN=8) in three of the four tumours (#615, #635 and #709), and within a region of single copy gain in the remaining tumour (#745)." (PMID 24777035, 2014). "Specifically, we characterized the structure of the recurrent amplification around MDM2, which was found in 4 of 10 invasive tumours." (PMID 24777035, 2014). "The selectivity on tumor cells would be given by the presence of mdm-2 on the plasma membrane of these cells, which is related to the role of mdm-2 in E-cadherin ubiquitination and degradation." (PMID 24885242, 2014). "MDM2 is located in many tissues, such as brain, placenta, uterus and lymph node, and is upregulated in many tumor issues." (PMID 24124579, 2013).
tumor (continued). "With such broad and complex tumorigenic effects, it is not surprising that a search in the Pubmed database indicates that 90% of Mdm2-related publications refer to a tumor context." (PMID 24303114, 2013). "A mouse xenograft tumor model that overexpressed beta-arrestin, a known regulator of MDM2, showed increased MMP9 activity with more aggressive tumors." (PMID 24236052, 2013). "Due to its critical role in tumor development, understanding the mechanism by which Mdm2 expression is controlled will lay the foundation for therapeutic strategies by targeting Mdm2 for cancer management." (PMID 23912475, 2013). "The frequency of MDM2 G/G in their study was somewhat greater in the tumor population than in the control group consisting of healthy individuals, although the values those researchers obtained differ very little from the levels noted in our investigation." (PMID 23356517, 2013). "Five meta-analyses have been published addressing the MDM2 SNP309 polymorphism and the risk of various types of tumor." (PMID 23624782, 2013). "PRDM2 is a member of the PRDM (PRDI-BF1 and RIZ domain containing) family, one member of which, PRDM5, down-regulates MDM2 gene expression to inhibit tumor cell clonogenicity and cell proliferation." (PMID 24124579, 2013). "These are necessarily limited in number because of the rarity of the tumor, but nevertheless, a substantial number had MDM2 and/or MDM4 copy-number amplification." (PMID 24321497, 2013).
tumor (continued). "This therefore invites a careful characterization of these markers in tumours when considering in-vivo experimental evaluation of novel MDM2-specific or dual target MDM2/MDMX blocking compounds." (PMID 24330579, 2013). "Immunohistochemical staining for MMP9 and MDM2 was performed using archived tumor blocks from 321 women who underwent surgical resection for IDC at the First Affiliated Hospital of Nanjing Medical University, China between January 2002 and December 2003." (PMID 24236052, 2013). "The tumor spectrum was only modestly altered in some of the genotypes of mice when Mdm2 was heterozygous." (PMID 23029416, 2012). "Recently, mice “humanized” to carry a human-specific SNP in the Mdm2 promoter allowed to demonstrate its importance on tumor onset." (PMID 22761580, 2012). "During serum deprivation, miR-17 prolonged tumor cell survival, induced angiogenesis and promoted stem-like cell aggregation by repressing expression of MDM2 and PTEN and modulating HIF-1α levels." (PMID 23391506, 2012). "We have observed a significant delay in tumor development in Mdm2+/−Arf−/− mice as compared to Mdm2+/+Arf−/− mice, but tumor spectrum was similar between these two genotypes." (PMID 23029416, 2012).
tumor (continued). "We will illustrate the importance of these interactions with Mdm2 and discuss how this is important for tumor progression, cellular proliferation in cancer." (PMID 23208375, 2012). "On the other hand, because of its effect on MDM2, the CDKN2A product, ARF, acts as a tumor suppressor; consequently its loss is associated with neoplasms." (PMID 22829758, 2012). "Another limitation with Nutlin is that although Nutlin kills cancer cells that express elevated Mdm2, tumor cells overexpressing MdmX have poor response to Nutlin due to its low binding affinity for MdmX compared to Mdm2." (PMID 22410433, 2012).